DDR1 (discoidin domain receptor tyrosine kinase 1)
Diseases named in the same sentence as DDR1 in open-access papers (continued):
Sharing a sentence is not in itself a finding about the gene and the disease.
breast carcinoma (continued). "Notably, DDR1 has been implicated in a signaling pathway that drives breast epithelial differentiation in cooperation with RUNX1, a key regulator of epithelial–mesenchymal transition (EMT) in breast cancer." (PMID 41492134, 2026). "Notably, DDR1 exhibits a subtype-dependent regulatory role in breast cancer cell proliferation." (PMID 40563472, 2025). "As HER2, DDR1/2, and EGFR are associated with metastasis of breast cancer, one could assume that the enhanced activity of these receptor tyrosine kinases mediates the enhanced migration, invasion, chemotaxis, and metastasis to bone in the AKT3 knockdown 231-BO cells." (PMID 33670586, 2021). "Finally, we will test whether the simultaneous silencing of MT1-MMP and overexpression of DDR1 in basal-like breast carcinoma cells are able to restore apoptosis to a level similar to that observed in luminal-like breast carcinoma cells." (PMID 31130862, 2019). "Interestingly, we show that for Estrogen Receptor (ER) negative breast cancer patients, a low DDR1 expression is associated with a worse relapse-free survival." (PMID 31130862, 2019). "DDR1 activity could also promote homing of disseminated tumour cells in the liver upon collagen deposition to support β‐catenin‐dependent cell survival, as documented for other extracellular matrix components, such as tenascin C in metastatic breast cancer." (PMID 29438985, 2018). "In accordance with these in vitro findings, DDR1 and IR expression levels are strongly correlated in breast cancer specimens, and especially in cancers with aggressive characteristics, suggesting that the DDR1 - IR axis could be a valuable therapeutic target in human breast cancer." (PMID 28591735, 2017). "As a novel necroptosis inducer, DDR1-IN-1 is capable to induce necroptosis in MPNST cell lines S462, ST8814, T265, STS26T, breast cancer cell line MCF-7, and glioblastoma cell line U-87." (PMID 40025071, 2025). "Similarly, DDR1 mutations in breast cancer, estimated to occur in of 2%–4% of cases, may also be underreported as many genomic studies on breast cancer have not explicitly explored DDR1." (PMID 40614729, 2025). "In breast cancer, PI3KCA/AKT1 activation confers resistance to the CDK4/6 inhibitor Palbociclib, with DDR1 playing a pivotal role in this resistance." (PMID 40563472, 2025). "Downregulation of ERK signaling by miR-199b-5p inhibits DDR1 expression, suppressing EMT and tumor metastasis in prostate and breast cancer cells." (PMID 40563472, 2025). "Another breast cancer study recently revealed that collagen-induced DDR1 upregulated CXCL5, which promoted the formation of NETs and enhanced Treg infiltration, thereby facilitating the growth and metastasis of breast cancer." (PMID 38136314, 2023). "For instance, DDR1-mediated STAT3 activation is required for bladder tumor cell colonization to the lung and for metastatic reactivation of breast cancer cells." (PMID 34941574, 2022). "In vitro 3D cell culture demonstrated that the DDR1 enhances chemo-resistance by the STAT3 and NF-kB signaling pathway in Jurkat cells and T47D breast cancer cells." (PMID 35267698, 2022). "DDR1 ablation in MMTV-PyMT mice, a transgenic model of luminal B breast cancer, accelerated tumor growth and lung metastasis." (PMID 35004699, 2021). "HER2, DDR1/2, and EGFR are receptor tyrosine kinases which are frequently upregulated in breast cancer and are activated by various ligands e.g., heregulin, collagens, or EGF, respectively." (PMID 33670586, 2021). "Whereas DDR1 play a pro-apoptotic role, DDR2 has been shown to have a pro-metastatic role in breast carcinoma." (PMID 35004699, 2021). "Luminal breast cancer MCF-7 cells and basal-like breast cancer MDA-MD-231 cells express high and low levels of DDR1 and low and high levels of MT1-MMP, respectively." (PMID 33917302, 2021).
breast carcinoma (continued). "A recent study revealed that TM4SF1 coupled with DDR1 was shown to promote cancer stem cell traits and metastatic reactivation and by PKCα-dependent JAK2/Stat3 signalling in breast cancer." (PMID 33153498, 2020). "In fact, type I collagen can activate DDR1 to induce the expression of BIK, a pro-apoptotic member of the BCL-2 protein family, thereby triggering apoptotic cell death in these breast cancer cell lines." (PMID 32582700, 2020). "Taken together, these data suggest that in basal-like breast carcinoma MDA-MB-231 cells, DDR1 activity and shMT1-MMP are able to synergize and increase collagen-induced apoptosis." (PMID 31130862, 2019). "Previous works have shown that MT1-MMP was able to cleave DDR1, and that depletion of MT1-MMP was able to increase apoptosis in basal-like breast cancer cells." (PMID 31130862, 2019). "DDR1 is a unique member of RTK family and was first identified during a search for tyrosine kinase proteins expressed in human breast carcinoma." (PMID 31116512, 2019). "As expected and at the opposite of the luminal-like MCF-7 breast cancer cells, MDA-MB-231 cells expressed MT1-MMP at a high level and DDR1 at a very low level." (PMID 31130862, 2019). "In breast cancer cells, it was recently shown that the tetraspanin TM4SF1 promotes clustering of DDR1; however, in this scenario the DDR1 ectodomain was necessary for interaction with TM4SF1, while the transmembrane and cytoplasmic regions were dispensable." (PMID 28590245, 2017). "We recently reported that, in breast cancer cells, IGF-1R functionally crosstalks with DDR1 and this interaction increases IGF-1R stability and enhances protumorigenic actions of IGF-1." (PMID 28591735, 2017). "We showed that incubation with the conditioned medium from CAFs from human breast cancer was able to activate IGF-IR, AKT, and upregulate DDR1 in breast cancer cells." (PMID 26655502, 2016). "In MDA-MB-231 breast cancer cells, type IV collagen induces MMP-2 and MMP-9 secretion and invasion through a DDR1 and Src-dependent pathway." (PMID 27014069, 2016). "Here we confirm that, in breast cancer cells, miR-199a-5p reduces the activity of a luciferase construct containing the 3′-UTR of the DDR1 mRNA." (PMID 26655502, 2016). "Moreover, accumulating evidence using Matrigel or type I collagen as matrix barriers suggests that DDR1 plays a promoting role in invasion of a variety of human cancers including glioma, hepatocellular, squamous epidermoid, colorectal, lung, prostate, breast carcinomas." (PMID 27014069, 2016). "We identified two breast carcinoma tumor cells, T47D and MCF7, which demonstrated high DDR1 and low TGFBI, similar to BXPC3." (PMID 25369402, 2014). "Indeed, we found that signatures indicative of DDR1 and STAT3 signaling were increased in lung compared to brain metastases of breast cancer patients." (PMID 41826695, 2026). "High DDR1 expression correlated with poor prognosis in breast cancer patients, and increased CXCL5 expression correlated with an increased number of malignant phenotypes of breast cancer cells." (PMID 40391215, 2025). "In the absence of another collagen receptor, integrin, DDR1 can upregulate the MAPK pathway to promote breast cancer cell adhesion to surrounding tissues, independent of collagen receptor signaling." (PMID 40563472, 2025). "A previous report indicated that DDR1 inhibitors were currently under clinical testing for multiple indications (merestinib against metastatic breast cancer [NCT03292536], merestinib against HR+ or HER2– breast cancers [NCT02791334])." (PMID 40603853, 2025). "This notion is based on the hypothesis that DDR1 and CBFβ operate within the same pathway as RUNX1, contributing to cellular differentiation and structural stability in breast cancer." (PMID 40614729, 2025). "For instance, in luminal breast carcinoma, COLIVα5 promotes tumor proliferation through the non-integrin receptor DDR1." (PMID 39769286, 2024).
breast carcinoma (continued). "Through interaction with DDR1, COLIVα5 supports the Warburg effect of tumor cells by influencing c-Myc phosphorylation and regulation of p38 Mitogen-Activated Protein Kinase (MAPK), which are essential for breast cancer progression." (PMID 39769286, 2024). "DDR1 depletion inhibits cell growth and cell cycle progression and enhances the sensitivity of PIK3CA/AKT1 mutant cells to palbociclib in estrogen receptor (ER)-positive, HER2-negative breast cancer." (PMID 37709489, 2023). "DDR1 regulates multi-organ site metastatic reactivation of breast cancer by non-canonical signaling independent of its kinase activity." (PMID 35140331, 2022). "Moreover, a recent study in breast cancer reported DDR1 to be an interacting partner of ERBB2, and upregulation of DDR1 is one of the compensatory survival mechanisms in lapatinib-resistant tumors." (PMID 35664781, 2022). "The invasion of breast cancer cells is regulated by DDR1, and DDR1 kinase activity is not required for invadosome formation or activity." (PMID 35140331, 2022). "Unlike tumor xenograft animals, DDR1 knock-out in genetically modified MMTV-PyMT mice promotes spontaneous mammary tumor development, consistent with a DDR1 negative function during tumor initiation." (PMID 35936735, 2022). "Importantly, the authors reported an inverse correlation between DDR1 tumor expression and CD8+ T cells intra-tumoral levels in a cohort of breast cancer patients, highlighting the clinical relevance of their findings." (PMID 35936735, 2022). "Interestingly, DDR1 signaling has also been shown to enhance chemoresistance of breast cancer cells via NFκB-mediated expression of cyclooxygenase-2 (COX-2), and downregulation of DDR1 significantly enhanced drug sensitivity." (PMID 34805157, 2021). "Moreover, DDR1 undergoes cleavage by MT1-MMP, which is highly expressed in basal-like breast carcinoma cells." (PMID 35004699, 2021). "In breast cancer cells, in a pathway involving the CD9 tetraspanin, DDR1 induces cell migration." (PMID 33917302, 2021). "This miR-199a-5p: DDR1 inverse correlation was previously reported in other cancer types like colorectal cancer, hepatocellular carcinoma, and breast cancer, but not in ovarian cancers." (PMID 34837026, 2021). "In the same vein, targeting DDR1 alone or in combination with other chemotherapies have been suggested in several neoplasms, including metastatic colorectal cancer, K-RAS driven lung adenocarcinoma, and breast carcinoma." (PMID 32244515, 2020). "Referring to MAPK on the other hand, we could show recently that blockade of DDR1 and MAPK components act synergistically in sensitizing breast cancer cells for doxorubicin and mitoxantrone toxicity upon cell binding to collagen." (PMID 33287446, 2020). "DDR1 induces growth suppression and apoptosis by increasing the expression of the pro-apoptotic mediator BCL2-family member BIK in noninvasive luminal-like breast carcinoma cells." (PMID 32492656, 2020). "DDR1 is also a key factor in collagen-induced apoptosis in noninvasive luminal-like breast carcinoma cells." (PMID 31130862, 2019). "We have previously shown that in 3D collagen matrix, DDR1 plays a key role as it promotes cell growth suppression and apoptosis through the upregulation of the pro-apoptotic mediator BIK in noninvasive luminal-like breast carcinoma cells." (PMID 31130862, 2019). "In contrast, constitutive MT1-MMP-mediated DDR1 shedding was found to regulate collagen-induced signaling when DDR1 and MT1-MMP were co-expressed in COS1 cells, whereas MT1-MMP was suggested to be one of several DDR1 sheddases and regulators in HC1806 breast cancer cells." (PMID 31137480, 2019). "In the case of the basal-like breast carcinoma cells, collagen proteolysis by MT1-MMP, the low expression of DDR1, and its cleavage by MT1-MMP could contribute to cell survival in the interstitial microenvironment." (PMID 31130862, 2019).
breast carcinoma (continued). "Data showed that overexpression of DDR1 induced a decrease in cell growth and an increase in BIK expression, suggesting that moderate expression level of full length DDR1 in basal-like breast carcinoma provides them with a capacity to resist to collagen-induced cell growth suppression and apoptosis." (PMID 31130862, 2019). "Since DDR1 was shown to induce cell signaling, e.g., via the IGF axis in breast cancer, the insensitivity of W1CR cells to ILK inhibition could thus be explained." (PMID 31779287, 2019). "Since MT1-MMP is involved in DDR1 cleavage, partially protecting cells from the type I collagen induced apoptosis observed in the luminal breast cancer cell line MCF-7, we then investigated the effect of MT1-MMP depletion on DDR1 expression profile in the basal-like cell line MDA-MB-231." (PMID 31130862, 2019). "We have then suggested that the acquisition of mesenchymal features including the downregulation of DDR1 and the overexpression of collagenolytic proteinases such as MT1-MMP provide breast carcinoma cells with an increased capacity to resist to apoptosis induced by 3D collagen matrix." (PMID 31130862, 2019). "The expression levels of E-cadherin, vimentin, DDR1, DDR2, α2 integrin, α11 integrin, COL1A1, MT1-MMP, BIK, estrogen receptor α, progesterone receptor, and HER2 mRNAs in 58 breast cancer cell lines were analyzed in silico, by using the Broad-Novartis Cancer Cell Line Encyclopedia (CCLE) database." (PMID 31130862, 2019). "In addition to integrin-mediated signaling, collagens bind to discoidin receptor 1 (DDR1), a dimeric transmembrane tyrosine kinase which is overexpressed in PDAC, as well as breast cancers." (PMID 30200666, 2018). "Taken together, our data suggest that in MCF-7 and T-47D breast carcinoma cells, when seeded on collagen 1, DDR1 but not β1-integrin activates ERK1/2 promoting Kv10.1 and Orai1 overexpression leading to persistent MAPK signalling activation." (PMID 29872495, 2018). "Besides binding to DDR1 itself, TM4SF1 has been shown to support clustering of collagen I-bound DDR1 receptors in breast cancer." (PMID 30200666, 2018). "We next evaluated whether DDR1 expression could modulate the biological effects of insulin and IGF-2 in breast cancer cells." (PMID 28591735, 2017). "In vitro investigations revealed that these compounds potently inhibited the proliferation of cancer cell lines expressing high levels of DDR1, including A549 and NCI-H23 lung carcinoma, MDA-MB-435, MCF-7, and T47D breast carcinoma and HCT116 colon carcinoma cells." (PMID 27014069, 2016). "Studies in triple-negative breast cancer cells revealed a novel H-Ras/ZEB1/DDR1 network that contributes to breast cancer progression in Ras-dependent hyperactive signaling." (PMID 27014069, 2016). "Indeed, in breast cancer cells (MCF-7 and MDA-MB-231) IGF-I induced significant increase of DDR1 protein expression, in a time and dose dependent manner." (PMID 26655502, 2016). "Our previous data indicate that, in breast cancer cells, DDR1 interacts with IGF-1R and positively modulates IGF-1R expression and biological responses, suggesting that the DDR1-IGF-IR cross-talk may play an important role in cancer." (PMID 26655502, 2016). "Moreover, stable transfection of breast cancer cells with the IGF-II gene resulted in constitutively activated AKT, reduced miR-199a-5p levels, and markedly upregulated DDR1 expression." (PMID 26655502, 2016). "In breast cancer, a negative correlation between DDR1 and Zeb1 was found in carcinoma tissues." (PMID 33917302, 2021). "Although both breast cancer cells in this study react differently to the ITGB1-kd with respect to DDR1, either by its upregulation (MDA-MB-231) or a slight downregulation (MCF-7), both cell lines confer COL1 binding into an active DDR1-mediated signaling via the MAPK pathway." (PMID 32668815, 2020).
breast carcinoma (continued). "Finally, the combined overexpression of DDR1 and depletion of MT1-MMP in MDA-MB-231 cells synergistically increased collagen-induced cell growth suppression and apoptosis to a level similar to that observed in luminal breast carcinoma." (PMID 31130862, 2019). "Since MDA-MB-231 cells slightly express DDR1, we assume that the weak expression of this receptor is a key parameter explaining why type I collagen fails to impair growth and survival of these basal-like breast carcinoma cells." (PMID 31130862, 2019). "In accordance with this hypothesis, the enforced expression of MT1-MMP in luminal-like breast carcinoma cells abrogates the BIK-mediated apoptosis, suggesting that the degradation of type I collagen could be responsible of a lower DDR1 activation and thus a decreased apoptosis." (PMID 31130862, 2019). "Related to DDR1, it has been identified as a key sensor that monitors the cellular microenvironment and triggers apoptosis through the induction of the pro-apoptotic Bcl-2-interacting killer protein (BIK) in luminal breast cancer cells within a collagen three dimensional culture system." (PMID 27014069, 2016). "Notably, we previously showed that, in breast cancer cells, IGF-I may upregulate DDR1 expression through a signaling pathway involving the DDR1 regulatory miR-199a-5p." (PMID 27384677, 2016). "In order to determine whether DDR1 may functionally interact with the IGF-IR, we first evaluated by immunoblot DDR1 and IGF-IR expression in a panel of IGF-I-responsive human breast cancer cell lines (MCF-7, T47D, ZR-75, MDA-MB-157, MDA-MB-231, BT-474), and in human HepG2 hepatoblastoma cells." (PMID 25840417, 2015). "According to these results, the insulin-induced phosphorylation of DDR1 has been described in cancer cells, and the constitutive phosphorylation of DDR1 is present in several oral squamous cell carcinoma cells but not in other cell types, such as breast cancer T24D cells." (PMID 36675255, 2023). "Some studies have shown that adhesion can occur in a DDR-independent manner, e.g., in breast cancer, the adhesion of MCF-7 cells to collagen is predominantly driven by β1 integrin rather than DDR1." (PMID 33917302, 2021). "In breast cancer cells, silencing of TM4SF1 did not inhibit the kinase activation of DDR1 on cell clustering, suggesting that DDR1 had its own ability." (PMID 28368050, 2017). "Herein we found that, in breast cancer cells, exposure to IGF-I induced significant upregulation of DDR1 protein, which was not accompanied by concomitant similar changes in DDR1 mRNA expression." (PMID 26655502, 2016). "The positive correlation of DDR1 with IGF-IR and IGFBP2, but not with AKT, INSR or IGFBP5, was further confirmed in the TCGA breast cancer dataset." (PMID 26655502, 2016). "This interaction was shown to occur in a panel of human breast cancer cells as well as in mouse fibroblasts (R- cells) co-transfected with the human IGF-IR and DDR1, indicating that it is not cell-specific." (PMID 27384677, 2016).